NOTCH2 (notch receptor 2)
Diseases named in the same sentence as NOTCH2 in open-access papers (continued):
Sharing a sentence is not in itself a finding about the gene and the disease.
Alagille syndrome (continued). "For example the Alagille syndrome is an autosomal dominant disorder associated with mutations or deletions of Jag1 gene or, in less than 1% of cases, with Notch2 mutations." (PMID 19936191, 2008). "Alagille Syndrome (AGS) is a systemic disease caused by heterozygous mutations in the Jagged 1 gene (JAG1) or Notch2 gene (NOTCH2)." (PMID 18937870, 2008). "Recently, heterozygous NOTCH2 mutations were identified in a subset of Alagille syndrome patients who lack JAG1 mutations." (PMID 18365007, 2008). "Alagille syndrome is caused by mutations in JAG1 on chromosome 20 or NOTCH2 on chromosome 1." (PMID 37101309, 2023). "Interestingly, Alagille syndrome (ALGS) is a genetic disease resulting from Notch2 and/or Jagged1 mutation." (PMID 29033846, 2017). "However, mice doubly heterozygous for a Jag1 null allele and a Notch2 hypomorphic allele exhibited most of the clinically relevant features of Alagille syndrome, including bile duct paucity." (PMID 18365007, 2008). "Interestingly, mutations in JAG1 and NOTCH2, the human homologs of the main ligands and receptor in the zebrafish notochord, lead to vertebrae malformations in human Alagille Syndrome." (PMID 35658971, 2022). "Alagille syndrome (ALGS) is a rare multisystem disorder most commonly resulting from pathogenic variants in JAG1 and, less frequently, NOTCH2." (PMID 41961327, 2026). "Alagille syndrome (ALGS) is a rare autosomal dominant genetic disease caused by pathogenic variants in two genes: Jagged Canonical Notch Ligand 1 (JAG1) and Notch Receptor 2 (NOTCH2)." (PMID 39202394, 2024). "Alagille syndrome, caused by variants in JAG1 or NOTCH2, is a well-recognized phenotype characterized by highly penetrant posterior embryotoxon and liver dysfunction along with cardiac and vertebral anomalies." (PMID 37895297, 2023). "Alagille syndrome is a rare multifaceted disorder that occurs mostly due to mutations in the JAG1 gene and rarely due to mutations in the NOTCH2 gene." (PMID 37890331, 2023). "Alagille syndrome (ALGS) is an autosomal dominant disease characterized by a multisystem involvement including bile duct paucity and cholestasis, caused by JAG1 or NOTCH2 mutations in most of the cases." (PMID 37099537, 2023). "Liver disease in NAIC overlaps with the hepatic component of Alagille syndrome (AGS; OMIM #118450), an autosomal dominant disease caused by mutations in the notch signaling effectors JAG1 or NOTCH2 or the transcription factor HNF1B." (PMID 36656901, 2023). "NOTCH2 is also a possible receptor given that it acts as the receptor for JAG1 in other systems that are affected in Alagille syndrome." (PMID 36400760, 2022). "Alagille syndrome, caused by rare mutations in JAG1 and NOTCH2, includes failure to thrive within its phenotypic spectrum." (PMID 33682876, 2021). "In contrast to the haploinsufficiency observed in Alagille syndrome, Hadju–Cheney syndrome (HJCYS) results from frameshift or nonsense mutations in the NOTCH2 gene." (PMID 34200313, 2021). "Currently, approximately 94% of Alagille syndrome patients have variants of JAG1, while 1–2% of patients have NOTCH2." (PMID 34651015, 2021). "For instance, when the interaction between Notch-2 and Jagged-1 is missing, Alagille syndrome will occur, resulting in defects in the biliary duct tree during in the early stages of development." (PMID 34885623, 2021). "Alagille syndrome is caused by mutations in JAG1 and NOTCH2 with major clinical manifestations in the heart and liver, and characteristic facial features." (PMID 33226994, 2020). "The importance of Notch haploinsufficiency is underscored in studies of Alagille syndrome, which can be caused by heterozygous mutations in either JAG1 or NOTCH2." (PMID 32161758, 2020). "Alagille syndrome is an autosomal dominant multisystem disorder with variable phenotypic penetrance, caused by heterozygous mutations in JAG1 or NOTCH2, encoding for the components of the Notch signaling pathway." (PMID 31157196, 2019).
Alagille syndrome (continued). "The frequency of identifiable genetic mutations in patients with a clinically consistent diagnosis of Alagille syndrome is high, with JAG1 mutations identified in 94% and Notch2 mutations in 2% of affected individuals." (PMID 27855169, 2016). "Manteia returns no gene with all six features, but finds two candidates with five of them, including NOTCH2, which is known to be responsible for Alagille syndrome." (PMID 24038354, 2014). "It has been shown that patients with Alagille syndrome, caused by mutations in JAG1 or NOTCH2, develop calcific AVD." (PMID 29552567, 2014). "Such defects are strikingly similar to Notch-deficient zebrafish and mouse models which phenocopy the human Alagille syndrome (OMIM#118450), which itself is associated with JAGGED1 and NOTCH2 mutations." (PMID 22719264, 2012). "A phenotype similar to the Alagille syndrome and Jagged1/Notch2 mice is present in mice homozygous for Notch target Hey2 deletion, implying the existence of transcriptional specificity for individual Notch receptors." (PMID 19936191, 2008). "Further support for a critical role for the Notch2 gene in bile duct formation and/or maintenance comes from recent studies on Alagille syndrome patients." (PMID 18365007, 2008). "Alagille syndrome (ALGS) is a multisystem condition characterized by cholestasis and bile duct paucity on liver biopsy and variable involvement of the heart, skeleton, eyes, kidneys, and face and caused by pathogenic variants in the JAG1 or NOTCH2 gene." (PMID 37511516, 2023). "Notch-associated disorders include different types of severe disorders such as Alagille syndrome caused by mutations in both ligand JAG1 and receptor Notch2 and autosomal recessive spondylocostal dysostosis, caused by mutations in ligand DLL3, and many other members of the Notch-signaling pathway." (PMID 36506336, 2022). "In conclusion, these findings underline the need for genetic screening of family members and the regular surveillance in patients with Alagille syndrome associated with JAG1/NOTCH2 variants, including subjects with or without mild liver involvement." (PMID 35884482, 2022). "Mutations in NOTCH2 are responsible for Hadju–Cheney syndrome (OMIM #102500) and Alagille syndrome." (PMID 34039391, 2021). "It is interesting to note that the skeletal, facial and vertebral abnormalities of the Alagille syndrome correlate with arterial calcification, suggesting that Jag1 and Notch2 may also play a role in osteoblast and bone development." (PMID 19936191, 2008). "Alagille syndrome (ALGS) is a rare genetic disease with autosomal dominant transmission, mainly caused by pathogenic variants in two gene-encoding proteins involved in the Notch Signaling Pathway: Jagged Canonical Notch Ligand 1 (JAG1) and Notch Receptor 2 (NOTCH2)." (PMID 39202394, 2024). "Could single-gene analysis for JAG1, NOTCH2 (Alagille syndrome), SERPINA 1(A1ATd), DCDC2 (isolated neonatal sclerosing cholangitis), and ABCB4 (PFIC3) still be used to exclude these intrahepatic diseases and avoid diagnostic errors in the first step of the investigation?" (PMID 36292464, 2022). "However, Alagille syndrome was ruled out after neither JAG1 nor NOTCH2 gene mutations were identified." (PMID 31414320, 2019). "Alagille syndrome (ALGS) is an autosomal dominant disorder, with multisystem involvement, which usually occurs due to Notch signaling pathway defects, mostly due to JAG1 mutation (ALGS type 1), but rarely due to neurogenic locus notch homolog protein (NOTCH2) mutation (ALGS type 2)." (PMID 30828556, 2018). "Alagille syndrome (ALGS) is an autosomal dominant, multisystemic disorder due to haploinsufficiency in either the JAG1 gene (ALGS type 1) or the NOTCH2 gene (ALGS type 2)." (PMID 37890331, 2023). "Although genetic tests for liver cholestatic diseases were performed with negative results for Alagille syndrome (JAG1 and NOTCH2), a de-novo missense mutation of HNF1β gene was detected." (PMID 30791938, 2019).
Alagille syndrome (continued). "For example, except for the common disease gene JAG1 between Tetralogy of Fallot and Alagille syndrome, the two diseases interact through 5 PPIs with a p value < < 0.01 in the network, including JAG1 – NOTCH1, JAG1 – NOTCH2, JAG1 – NOTCH3, DLL1 - NOTCH2 and DLL1 – NOTCH3." (PMID 25539592, 2014).
glioma (51 papers, 2007 to 2025). A benign or malignant brain and spinal cord tumor that arises from glial cells (astrocytes, oligodendrocytes, ependymal cells). "Furthermore, distribution of the NOTCH1 and NOTCH2 mutations across grade III gliomas was also significantly dependent on H3-3B expression." (PMID 34771425, 2021). "Based on our results, the inhibition of Notch2 caused by NAC may contribute to glioma therapy and its prognosis." (PMID 30606241, 2019). "However, the molecular mechanisms underlying Notch2 regulation of glioma cell proliferation require further investigation." (PMID 25323114, 2014). "Thus, our current finding confirms our observation that Notch1 is a stronger tumor suppressor than Notch2 in a PDGF-driven mouse model of glioma and implies that Notch1 could partially compensate for Notch2 loss." (PMID 36358826, 2022). "Subsequently, ROC curve analysis suggested that the AUC values of WWTR1, STEAP3, SLC39A14, NOTCH2, IREB2, HIF1A, and FANCD2 were all 1.000, indicating their potential as diagnostic biomarkers for gliomas." (PMID 37978473, 2023). "In conclusion, we identify seven ferroptosis-associated genes (SLC39A14, WWTR1, STEAP3, NOTCH2, IREB2, HIF1A, and FANCD2) in gliomas, all of which are highly expressed." (PMID 37978473, 2023). "As Notch1 and Notch2 play a major role in the glioma tumorigenesis and in therapy resistance, we next examined the effects of X-rays and CII on the protein expression of NOTCH1 and NOTCH2 receptors." (PMID 36359750, 2022). "Changes in expression levels of Notch2 and changes in the signaling pathway have been found in glioblastoma, specifically the glioma stem cell population." (PMID 35610333, 2022). "In support of these observations in human brain tumor subtypes, simultaneous genetic inactivation of Notch1 and Notch2 or Rbpj accelerates the growth of PDGF-driven gliomas in mice." (PMID 36358826, 2022). "Various studies have demonstrated increased expression of distinct components of Notch signaling pathway (such as Notch1, Notch2, Dll1, Dll4 and Jag1) and Notch target genes (Hey1, Hey2, Hes1) in glioma cell lines or primary human glioma samples including GBM." (PMID 36010607, 2022). "Notch-2, on the other hand, was identified as a prognostic marker for glioma along with Notch-3, which also promotes glioma cell proliferation." (PMID 32290213, 2020). "The over expression of miR‐34c‐3p (miRNAs) strongly inhibits glioma invasion and promotes the S‐phase arrest, increases cell apoptosis and reduces Notch2 expression." (PMID 33047886, 2020). "Consistently, external expression of the active intracellular portion of NOTCH1 and NOTCH2 has a protective effect on glioma CSCs, while knock-out of these receptors increase radioresistance." (PMID 32796631, 2020). "NOTCH2 overexpression can inhibit glioma formation in mouse glioma models and HEY2 overexpression can reduce the proliferation of murine and human glioma cells." (PMID 33076453, 2020). "Notch1 loss-of-function mutations correlate with low-grade gliomas and have the best prognosis, in line with other studies where high expression of CSL, Notch1 or Notch2 sustains the tumor growth." (PMID 32796631, 2020). "An elevated miR-107 expression suppressed growth, migration and invasion abilities of glioma cells, directly targeting Notch2 and inhibiting Notch2, Tenascin-C, MMP-12 and Cox-2 expression." (PMID 30583549, 2018). "In glioma and medulloblastoma, miR-34a levels were lower than in normal brain tissue, which in turn directly bound to Notch1 and Notch2 3’-UTR and suppressed Notch1 and Notch2 expression." (PMID 29299142, 2017).
glioma (continued). "Of interest, siRNA targeting NOS2 blocked the increase in SOX2, Notch-2 and β-catenin expression in irradiated U87 glioma cells, thus inhibiting the stemness machinery for malignant progression." (PMID 28424427, 2017). "In glioma, expressions of the constitutively active intracellular domains of Notch1 or Notch2 protect glioma stem cells against radiation." (PMID 28038467, 2017). "Knockdown of Notch1 or Notch2 sensitized glioma stem-like cells to radiation and impaired xenograft tumor formation." (PMID 26273424, 2015). "By contrast, several studies have shown that Notch2 inhibits tumor cell growth by antagonizing Notch1 and that upregulation of Notch2 in U251 cells can suppress glioma cell proliferation." (PMID 25323114, 2014). "In conclusion, Notch2 silencing inhibited U87 glioma cell proliferation by inducing cell cycle arrest and apoptosis in vitro and in vivo." (PMID 25323114, 2014). "The current study confirmed the inhibition of glioma cell proliferation by downregulation of Notch2 in vitro and in vivo, thus providing valuable information for future studies on the role of Notch signaling in glioma." (PMID 25323114, 2014). "In the present study, it was found that Notch2 signaling in U87 human glioma cells increased the proportion of cells in the S phase and upregulated MCM2 and cyclin D1 protein expression levels; however, p21 protein expression was downregulated." (PMID 25323114, 2014). "Equally, knocking-down Notch1 or overexpressing Notch2 suppressed cell growth and invasion in addition to enhancing apoptosis of subcutaneously engrafted U251 and A172 glioma cells." (PMID 25601901, 2014). "The results of the present study indicate that the Notch2 signaling pathway is important in U87 human glioma cell proliferation." (PMID 25323114, 2014). "This phenotype was reversed by the overexpression of NICD of Notch1 or Notch2, confirming that Notch is essentially involved in the survival of glioma BTPCs post irradiation." (PMID 25601901, 2014). "Notch2 expression was downregulated in the U87 human glioma cells using the RNA interference method." (PMID 25323114, 2014). "The aim of the current study was to determine the role of Notch2 in human glioma cell proliferation in an attempt to provide a direction for the development of a novel molecular therapy." (PMID 25323114, 2014). "They proved that both upregulating of Notch1 and knocking down Notch2 had the effect of suppressing glioma cell growth and invasion as well as inducing apoptosis." (PMID 24053158, 2013). "OD and GBM showed distinct deletion patterns that converged to the NOTCH2 gene in both glioma subtypes." (PMID 17593975, 2007). "Our data propose NOTCH2 as a powerful new molecular test to detect prognostically favorable gliomas." (PMID 17593975, 2007). "NOTCH2, a member of the Notch family, mainly contributes to promoting tumor development in gliomas." (PMID 37978473, 2023). "Reduction in Notch1 or Notch2 levels also leads to radio-sensitive glioma stem cells." (PMID 35887547, 2022). "In glioma tissues and cells, the expression of mir-107 and mir21 is down-regulated, whereas overexpression of mir-107 can inhibit the migration, invasion, and tubulation of glioma cells by directly targeting Notch2 expression." (PMID 36421704, 2022). "Additionally, constitutive expression of the active intracellular domains of Notch1 or Notch2 protects glioma stem cells against radiation." (PMID 35887547, 2022). "The results have shown that miRNA clusters could promote the expression of TNC and COX-2 by activating Notch2, thereby increasing the angiogenesis and invasion of gliomas." (PMID 36421704, 2022). "Finally, treatment of U251 glioma cells for 24 h with both doses of ML2-SA1 increased the expression of the Notch2 active form." (PMID 35054871, 2022).